MMP2 (matrix metallopeptidase 2)
Diseases named in the same sentence as MMP2 in open-access papers (continued):
Sharing a sentence is not in itself a finding about the gene and the disease.
preeclampsia (continued). "Thus, decreased MMP-2 activity may also contribute to the pathophysiological vascular remodeling during preeclampsia, as previously suggested." (PMID 37628999, 2023). "This study showed that MMP2 polymorphisms do not influence the development of hypertensive disorders of pregnancy and additionally do not affect the responsiveness to antihypertensive therapy in hypertensive disorders of pregnancy, especially preeclampsia." (PMID 35885543, 2022). "In contrast, the MMP-2 -735 C>T polymorphism was not significantly different regarding frequency distribution of the allele and genotype between healthy pregnant women and women with preeclampsia." (PMID 34208487, 2021). "Downregulation of FLNB also contributes to decreased expression of ERK, MMP-2, and MMP-9, which in turn reduces placental trophoblast invasion in preeclampsia." (PMID 40638605, 2025). "The object of the present study was to reveal the role of MMP-2 and MMP-9 in the development of severe preeclampsia." (PMID 33381317, 2020). "In this regard, it was demonstrated increased MMP-2 levels in urine of preeclamptic women and increases MMP-2 levels in aminiotic fluid of women who subsequently develop preeclampsia." (PMID 31703340, 2019). "Plasma concentration of MMP-2 and MMP-9 at 20 weeks of gestation was measured in women with suspected preeclampsia." (PMID 28726716, 2017). "MMP-2 and MMP-9 have become of particular interest due to their frequent implications as key factors in the pathogenesis of preeclampsia." (PMID 28726716, 2017). "At delivery, urine concentrations of MMP-2 and MMP-9 were significantly elevated in women with severe preeclampsia compared to normal pregnancy, and this feature persisted 6 to 8 weeks after delivery." (PMID 28726716, 2017). "Higher amniotic fluid MMP-2 and TIMP-2 levels are found in women who eventually develop preeclampsia." (PMID 19698156, 2009). "In conclusion, higher levels of MMP-2 and TIMP-2 are found in the amniotic fluid of women prior to presentation of preeclampsia." (PMID 19698156, 2009). "Increases in MMP-2 and MMP-9 in response to estrogen and progesterone promote placentation, uteroplacental vascularization and fetal growth during healthy pregnancy, but are altered in preeclampsia (PE)." (PMID 41897317, 2026). "Decreased vascular MMP-2 and MMP-9 may lead to decreased vasodilation, increased vasoconstriction, hypertensive pregnancy, and preeclampsia." (PMID 35774422, 2022). "Moreover, few clinical studies have evaluated the role of MMP-2 and MMP-9 in the pathophysiology of preeclampsia." (PMID 31703340, 2019). "Increased MMP-2 and MMP-9 methylation is observed in villous samples of preeclamptic patients; this gene silencing explains the low concentrations of these enzymes and supports the trophoblast invasion defects seen in preeclampsia." (PMID 28726716, 2017). "A decrease in MMP-2 and MMP-9 interferes with the normal remodeling of spiral arteries at early pregnancy stages, leading to the initial pathophysiological changes observed in preeclampsia." (PMID 28726716, 2017). "We detected a higher frequency of the presence of SNPs in the NOS3 gene in the group of pregnant women with preeclampsia, but not in the MMP2 and MMP9 genes." (PMID 26317342, 2015). "We were not able to study MMP-2 levels in women with chronic hypertension without superimposed preeclampsia." (PMID 19698156, 2009). "Women who eventually developed preeclampsia showed increased levels of MMP-2 at 22 weeks but not at 26 weeks." (PMID 19698156, 2009). "Cardiac gene expression of Vcam, Edn1, Ccr2, Ctgf, Tgfb1, Tgfb2, Tgfb3, Bnp, Cybb, Mmp2, Mmp9, Timp1, Camk2a, Slc9a1, Nr3c2, and Nr3c1 was not different between mice who had a normal pregnancy and mice who had a preeclampsia-like pregnancy at 5 or 10 weeks postpartum (respectively)." (PMID 40425613, 2025). "However, no statistical difference in MMP-2 levels was found between patients with gestational hypertension and normotensive patients." (PMID 19698156, 2009).
preeclampsia (continued). "Invasion-related genes such as transcription factor Snail, matrix metalloproteinase 2 (MMP2) and matrix metalloproteinase 9 (MMP9) have been reported to play critical roles in EVT invasion and dysregulations of these genes may contribute to the etiology of preeclampsia and IUGR." (PMID 28959722, 2017).
Sepsis (38 papers, 2010 to 2025). Sepsis is defined as life-threatening organ dysfunction caused by a dysregulated host response to infection. "The aim of this study was to investigate the timely development of serum and skin MMP-2, -8 and -9 levels in human severe sepsis and their association with disease severity and mortality." (PMID 20356362, 2010). "It had been indicated that inhibition of MMP-9 and MMP-2 levels could effectively reduce the level of inflammatory cytokines in the brain and improve cognitive impairment caused by sepsis." (PMID 31213027, 2019). "Elevated blood serum concentrations of MMP9, MMP2, and TIMP4 are associated with a progressive course of NEC with sepsis." (PMID 40303487, 2025). "In our study, immunohistochemical analysis of the lung tissue of rats in the sepsis group showed significantly higher MMP-2 and MMP-9 positivity than the other 4 groups." (PMID 39860018, 2025). "Along these lines, RvD2 in murine model of sepsis increases MMP-2 and MMP-3 in infectious exudates (and references within)." (PMID 39294573, 2024). "Our study specifically highlights the differential expression of matrix metalloproteinases (MMPs), such as Mmp2-3, Mmp8-9, Mmp14, Mmp17, Mmp19, and Mmp28-29, with significantly higher expression in LPS-induced sepsis compared to CLP-induced sepsis." (PMID 37510271, 2023). "We found that sepsis enhanced the expression of E‐cadherin, ZO‐1, MMP2, and MMP9 but weakened that of TIMP‐2 and TIMP‐3." (PMID 37525933, 2023). "The analysis showed that NOS3, SIRT1, HSP90AA1, MMP9, MMP2, PTPRC, and TLR2 were associated with multiple organ damage in sepsis." (PMID 36406124, 2022). "In a severe sepsis rat model, the increase of BBB permeability was associated with elevated expression and activation of MMP-2/-9 in both cortex and hippocampus." (PMID 35269933, 2022). "In the animal model of sepsis, MMP-2 and MMP-9 were activated, blood-brain barrier (BBB) permeability increased, and BBB permeability was reversed by MMP inhibitor." (PMID 36142454, 2022). "In fact, the eventual mortality of patients has been associated with the elevated levels of MMP‐2, MMP‐9, MMP‐8, and TIMP‐1, as observed in the early stages of sepsis." (PMID 35818743, 2022). "In this study, we aimed to evaluate the diagnostic value of several MMPs (MMP-2, MMP-9, MMP-8) and TIMPs (TIMP-1 and TIMP-2) for equine colic, which is often associated with endotoxemia and sepsis in case of strangulating obstruction." (PMID 33488296, 2021). "Two important mediators of an inflammatory response in sepsis, MMP-2 and MMP-9 were determined in a dose-dependent manner." (PMID 30142934, 2018). "Gelatinases (MMP-2 and -9) have been related to sepsis so far although less attention has been paid to collagenases (MMP-1, - 13) and stromelysins (MMP-3, -10)." (PMID 24833564, 2014). "The form spliced to active conformation, the 62 kDa MMP-2, was found in all patients with severe sepsis on the first day (153.1 dU (53.2 to 373.9)) and on the fifth day (127.4 dU (47.4 to 318.2)), but not in controls." (PMID 20356362, 2010). "In severe sepsis, from intact skin suction blister and serum samples, MMP-2 and MMP-8 levels are elevated, whereas MMP-9 is suppressed." (PMID 20356362, 2010). "Active forms of MMP-2 and 9 were only present in patients with severe sepsis, and higher MMP-2 levels in skin blister and serum were associated with more severe organ dysfunctions." (PMID 20356362, 2010). "The levels of MMP-2 and -8 were up-regulated in severe sepsis in comparison to healthy controls in skin blister fluid and serum." (PMID 20356362, 2010). "The amounts of MMP-2, -8 and -9 were analyzed from serum at days 1, 4, 6, 8, and 10, and from skin suction blister fluid at days 1 and 5 from the beginning of severe sepsis." (PMID 20356362, 2010). "MMP-2/MMP-9 has been correlated with the severity of sepsis." (PMID 37504075, 2023). "Otherwise, MMP2 was demonstrated to be a key regulator in sepsis." (PMID 36110326, 2022).
Sepsis (continued). "After cecal ligation and perforation in rats, which induces a model of sepsis, Evans blue leakage was MMP2 and MMP9 dependent such that inhibition of these two enzymes could reverse the clinical features of sepsis-associated encephalopathy." (PMID 34594000, 2021). "In conclusion, we provided the experimental evidence that lidocaine could alleviate sepsis-induced ALI via activating AMPK/SOCS3 axis to inhibit the ASK1-p38-TF/MMP-2/9 signaling pathway." (PMID 34804364, 2021). "MMP-2 and MMP-9 blocker could reverse the increase of permeability of the blood-brain barrier and improve acute cognitive alteration associated with sepsis." (PMID 31213027, 2019). "MMP-2 and -8 are elevated in serum and blister fluid in severe sepsis, implying that they may play a significant role in the pathogenesis of severe sepsis and organ dysfunctions." (PMID 20356362, 2010). "Active forms of MMP-2 and -9 were present only in severe sepsis." (PMID 20356362, 2010). "In addition, endothelial damage and reactive oxygen species present in sepsis can trigger the activation of MMP-2." (PMID 20356362, 2010). "Taken together, these results indicate that lidocaine may promote the expression of SOCS3 in an AMPK-dependent manner, inhibiting the activation of the ASK1-p38-TF/MMP-2/9 signaling pathway to decrease the formation of thrombus and to alleviate sepsis-induced ALI." (PMID 34804364, 2021). "It is known that MMP-2 and MMP-9 levels increase in sepsis and show a positive correlation with the severity of the disease." (PMID 39860018, 2025). "Differential analysis of NOS3, MMP2, HSP90AA1, and SIRT1 in the sepsis kidney injury-control group (SKi-C) showed that the p-value were all <0.05, indicating differential expression." (PMID 36406124, 2022). "Differential analysis of HSP90AA1, MMP2, and MMP9 in the sepsis spleen injury-control group (SSp-C) showed that the p-value were all <0.05, indicating differential expression." (PMID 36406124, 2022). "Not only this, but MMP‐8 levels have also been evidenced to be increased alongside MMP‐9, MMP‐2, and TIMP‐1 during early sepsis, a condition which has eventually been related to patient mortality." (PMID 35818743, 2022). "Higher MMP-2, MMP-8, MMP-9, MMP-10, TIMP-1 and MMP-10/TIMP-1 were seen in severe sepsis compared to controls." (PMID 34043679, 2021). "In a pig model of ARDS, suppression of PMN proteases, including matrix metalloproteinase-2 (MMP-2), MMP-9 and elastase, effectively suppressed the development of sepsis and ARDS." (PMID 33072112, 2020). "This is the first longitudinal study reporting the levels of MMP-2, MMP-8 and MMP-9 in the patients with severe sepsis." (PMID 20356362, 2010). "We measured the MMP-2, MMP-8 and MMP-9 levels during human severe sepsis and after recovery in serum and locally in skin using the suction blister method." (PMID 20356362, 2010). "Treatment with MMP-2 and MMP-9 inhibitors or MMP-2 or MMP-9-specific inhibitors in a rat model of sepsis reversed MMP-induced cognitive changes to BBB permeability, brain inflammatory responses, and sepsis." (PMID 36445634, 2023). "Furthermore, pharmacological inhibition of MMP-2/-9 reversed the increase of BBB permeability and improved acute cognitive performance in this rat sepsis model." (PMID 35269933, 2022). "MMP-2 concentrations in the group negative for sepsis were 55.3 (42.3–72.1) ng/ml in plasma and 7.8 (0.0–23.90) ng/ml in peritoneal fluid (PF), respectively." (PMID 33488296, 2021). "MMP-2 has been shown to be involved in inflammation, recruitment of inflammatory cells, permeability and remodeling in lung and TIMP-1 has been studied as a prognostic factor for sepsis." (PMID 34502521, 2021). "Our results show an increase in the MMP9 activity without a change in the MMP2 activity in the animals' liver of the sepsis group." (PMID 30524657, 2018).
Sepsis (continued). "• Levels of MMP-2 and MMP-8 were up-regulated in severe sepsis in comparison with healthy controls, both in skin blister fluid and in the serum, whereas MMP-9 levels were lower in serum in sepsis from the fourth day onwards." (PMID 20356362, 2010). "• Non-surviving patients had higher MMP-2 levels in skin blister fluid during sepsis than survivors." (PMID 20356362, 2010). "The main findings were the levels of MMP-2 and MMP-8 were up-regulated in severe sepsis both in skin blister fluid and in the serum, MMP-2 levels were higher in skin blister fluid as well as in serum in more severe organ failures, and at three and six months the MMP levels had returned to normal." (PMID 20356362, 2010). "Therefore, in severe sepsis, BBB dysfunction is related to the activities of MMP-2 and MMP-9." (PMID 35295600, 2022). "Based on our data, the levels of MMP-2 in blister fluid samples were higher in non-survivors and we have previously shown that re-epithelization of blister wounds is delayed in non-surviving severe sepsis patients." (PMID 20356362, 2010). "The activation of MMP-2 and MMP-9 by LPS induces the release of TNF-α, which can raise MMP-2 and MMP-9 levels in the blood of patients with sepsis in response to a Gram-negative bacterial infection." (PMID 37504075, 2023). "Respectively, a study has been reported that in patients with gram-negative bacteria, the severity of sepsis depends on the increasing levels of pro-MMP-9, pro-MMP-2, and the activated forms of MMP-9." (PMID 30142934, 2018). "Active forms of MMP-2 and MMP-9 are only found in some patients with severe sepsis, but not in controls." (PMID 20356362, 2010).
esophageal cancer (37 papers, 2010 to 2025). A primary or metastatic malignant neoplasm involving the esophagus. "At last, 12 associations (MMP-2 rs243865 with esophageal cancer and LC, MMP-7 rs11568818 with bladder and CC, and MMP-9 rs3918242 with BC) were rated as strong evidence for cancer risk, 7 as moderate evidence, and 15 as weak." (PMID 35574300, 2022). "It was strong for MMP-2 rs243865 with LC and esophageal cancer risk among the Asian populations in the dominant and allelic models." (PMID 35574300, 2022). "High MMP-2 and -9 levels were associated with esophageal carcinomas and breast, oral, bladder, skin, larynx cancer." (PMID 34305611, 2021). "Genetic polymorphisms in STK15 and MMP-2 have been associated with increased risk of esophageal cancer in Mongolia." (PMID 24281163, 2010). "Finally, 12 associations (MMP-2 rs243865 with esophageal cancer risk and LC risk, MMP-7 rs11568818 with bladder risk and CC risk, and MMP-9 rs3918242 with BC risk) were rated as strong evidence, 7 as moderate evidence, and 15 as weak." (PMID 35574300, 2022). "Recent reports have indicated that SPINK7 is a serine protease inhibitor having ability to inhibit uPA and MMP2 activities, which plays important roles in tumorigenesis and development of oesophagus cancer." (PMID 40147022, 2025). "In esophageal carcinoma KYSE150 cells, siRNA against MMP2 caused inhibition of the mRNA and protein expression of MMP2, leading to reduced invasion and migration of these cells." (PMID 36677584, 2023). "It has been reported that MMP2 expression in esophageal cancer is higher than the corresponding esophageal epithelium." (PMID 35397606, 2022). "Non-cytotoxic DADS concentrations (<68 μM) block the invasion and migration of esophageal carcinoma cells OE19 by downregulating the expression of the MMP2 and MMP9 metalloprotease genes." (PMID 36559076, 2022). "In situ gelatine gel profiles show that MMP2 and MMP9 gelatinolytic activity is enhanced in oesophageal squamous cell carcinoma and closely associated with vascular invasion in oesophageal cancer." (PMID 33995637, 2021). "ATF3 has been reported to affect the degradation of MMP2 at the protein level via the ATF3/MDM2/MMP-2 complex in esophageal cancer cells." (PMID 29966001, 2018). "In esophageal carcinomas, AurA triggers tumor cell migration through MMP-2 (matrix metalloproteinase 2) secretion via p38/Akt pathway activation." (PMID 30250494, 2018). "In addition, the expression of cyclin D1, MYC, MMP2, and molecules involved in the NF‐κB signaling pathway was increased in esophageal cancer cells, similarly as observed for PD‐L1." (PMID 40790948, 2025). "Similarly, HIF-1α siRNA decreases MMP-2 expression in esophageal cancer Eca109 cells in a hypoxic model with CoCl2 at 6, 12, and 24 h." (PMID 38069210, 2023). "Also, in oesophageal cancer, it stimulates the release of MMP-2 and MMP-9, increasing the invasiveness of cancer cells." (PMID 37686525, 2023). "In addition, protein expression of proliferating cell nuclear antigen (PCNA), matrix metalloproteinase (MMP-2), and E-cadherin in esophageal cancer cells was determined by Western blot analysis." (PMID 30940778, 2019). "In esophageal cancer-related studies, DCLK1 promotes EMT phenotype transformation through the MAPK/ERK/MMP2 pathway." (PMID 37239162, 2023). "By activating both a non-specific tyrosine phosphatase inhibitor and a specific PTP1B inhibitor, it significantly reduces the secretion of MMP-2 and MMP-9 from leptin-stimulated oesophageal cancer cells, inhibiting cancer invasion through this mechanism." (PMID 37686525, 2023). "In order to demonstrate the mechanism of QGS inhibiting cell mobility of ESCC cells, We also studied two protein pathways in which MMP2 and MMP9, these are closely related to esophageal cancer infiltration and metastasis." (PMID 31110076, 2019). "FOXM1c modulates oesophageal cancer invasion and migration by regulating IRF1 transcription and subsequently MMP2/9 expression." (PMID 30485581, 2019).
esophageal cancer (continued). "Genetically altering FOXM1c expression strongly affected oesophageal cancer metastasis by regulating IRF1 transcription, thus resulting in a change in MMP2/9 expression." (PMID 30485581, 2019). "The anti-migratory activities and suppressive effects on metastasis-related factors such as HER2, MMP2, MMP9, TM4SF3, CXCR4 of the absorbed AP components were revealed in esophageal cancer cells EC-109." (PMID 28405006, 2017). "We further found that depletion of V-ATPase V1E1 led to reduced expression of vimentin, MMP2, and MMP7, which are critical for metastasis of esophageal cancer cells." (PMID 27384996, 2016). "Hence, MMP-2 and E-cadherin expression can be regulated by HIF-1α through Snail, favoring invasion and metastasis of esophageal cancer cells under hypoxic conditions." (PMID 38069210, 2023). "Moreover, CDH1 was confirmed to repress the levels of the matrix metalloproteinase 2 (MMP2) and MMP9 in Esophageal cancer." (PMID 32714095, 2020). "Since MMP-2 and MMP-9 promotes cell migration and invasion, this may be possible mechanism in which hUCMSCs promote esophageal carcinoma cells invasion and thus may be a possible explanation for hUCMSCs promoted the lymph node metastasis of esophageal cancer." (PMID 25298750, 2014). "A previous report showed that ATF3 degrades the MMP protein by a proteasome-dependent pathway in esophageal cancer; however, ATF3 was unlikely to regulate the expression of MMP2 and 9 genes or the MMP2 and 9 protein stability in HCT116 cells, in this study." (PMID 29966001, 2018).